APOE (apolipoprotein E)
Diseases named in the same sentence as APOE in open-access papers (continued):
Sharing a sentence is not in itself a finding about the gene and the disease.
dementia (continued). "On the other hand, it should be noted that our study examined the possible pathophysiological process involved in a pre-dementia phase and thus our findings may suggest that high concentrations of ApoE would generate a more significant burden of amyloid beta deposition." (PMID 30897703, 2019). "APOE ε4 carriers (HR, 4.91; 95% CI, 2.53-9.56), adults with early-onset epilepsy (HR, 3.61; 95% CI, 1.12-11.60), multiple health comorbidities (HR, 1.956; 95% CI, 1.087-3.519), and those living with family (HR, 2.14; 95% CI, 1.08-4.20) received significantly earlier dementia diagnoses." (PMID 30452522, 2019). "When APOE-ε4 status was entered as a dichotomous covariate in the Cox regression models, the results per SD increase in physical activity score were not affected for any of the outcome variables (all-cause dementia, VaD, or AD) (data not shown)." (PMID 31630687, 2019). "Interestingly, APOE is not a risk factor for PD, which demonstrates its specificity for dementia risk." (PMID 30097731, 2018). "Second, previous studies have shown that age and APOE ɛ4 status may play a role in dementia." (PMID 30185213, 2018). "Furthermore, recent evidence suggests that the impact of foods on cognitive health outcomes may be modified by Apolipoprotein E ε4 genotype (APOE ε4), a major risk factor for dementia or by gender." (PMID 29966314, 2018). "However, when model 3 additionally adjusts for cardio/cerebrovascular or respiratory conditions, BMI, APOE ε4 and physical activity, the associations between sugar reduction and dementia risk were no longer significant." (PMID 30400288, 2018). "Moreover, the association of lower levels of Aβ1–38 with increased risk of dementia was more significant in carriers of the APOE-ε4 allele than in noncarriers." (PMID 29960604, 2018). "Given that this decline over almost three decades precedes estimations of the functional manifestations of prodromal AD 38,39, continued follow-up of NSHD will determine the age-specific incidence of clinical dementia in those with the APOE-ε4 allele, in comparison to those without." (PMID 29317609, 2018). "Fourth, the APOE gene subtype can play a regulatory effect in the injury and repair of synapses, and a decline in the number of dendrites in the hippocampus of ε4+ may be related to dementia." (PMID 30405900, 2018). "As predicted, positive age beliefs protected older individuals from developing dementia in the total sample, RR = .81, 95% CI = .67.97, p = .03, adjusting for the covariates of age, education, sex, race, cardiovascular disease, diabetes, baseline cognitive performance, and APOE ε4 status." (PMID 29414991, 2018). "However, when we analyzed the associations of the incidences of AD, PD, or dementia with APOE genotype, we found that TBI was not a risk." (PMID 30396335, 2018). "However, the results of a covariate-adjusted model confirm that the association between rare variants in dementia-causing genes and lower scores in cognitive tests appears to be independent of age, cohort, disease duration, or APOE status." (PMID 29692703, 2018). "Third, different phenotypes of the APOE gene can participate in the immune adjustment of the central nervous system; the immune response of the central nervous system in ε4+ is stronger than that in ε3+, and excessively strong immune responses can lead to brain injury and dementia." (PMID 30405900, 2018). "Also as predicted, positive age beliefs protected older individuals from developing dementia among APOE ε4 carriers, RR = .69, 95% CI = .50.94, p = .018, adjusting for the covariates of age, education, sex, race, cardiovascular disease, diabetes, and baseline cognitive performance." (PMID 29414991, 2018). "However, the association with APOE ε4 remains robust in ‘pure’ DLB cases who have Lewy bodies but minimal or low-level Alzheimer-related pathology, perhaps suggesting that APOE is correlated to dementia in a mechanism unrelated to the amyloid cascade." (PMID 30097731, 2018).
dementia (continued). "PD patients carrying rare variants in dementia-causing genes exhibited lower scores on cognitive tests than non-carrier PD patients (p = 2.0 × 10−4), independent of age at PD diagnosis, age at evaluation, APOE status or cohort." (PMID 29692703, 2018). "Although we did not assess ApoE genotype in this study, the association between SL‐CMBs and family history of dementia might indicate the underlying genetic factors." (PMID 29201555, 2017). "This again suggests that APOE should be a risk for all-cause dementia, and not just AD." (PMID 28291794, 2017). "Overall low total apoE levels were shown to increase the risk of AD and of other types of dementia in the Danish general population, but the question remains whether increased levels of all isoforms including apoE4 may be beneficial or not." (PMID 28137305, 2017). "First, information regarding several risk factors for dementia could not be obtained from the claims data, including information regarding cholesterol levels, family history, APOE, body mass index, and physical activity." (PMID 28162091, 2017). "This is because the evidence exclusively relies on observational studies which did not equally consider all important confounders (e.g. ApoE ε4 genotype) and which assessed the indirect relationship between vitamin D as surrogate for sunlight exposure and dementia risk." (PMID 28086755, 2017). "These observed neurodegenerative effects of PM2.5 (with the relative risk for global cognitive decline and all-cause dementia, respectively, increased by 81% and 92%) were not explained by differences in socioeconomic status, lifestyle, vascular risk factors and APOE alleles." (PMID 28140404, 2017). "Both the crude odds ratios (ORs) and ORs after adjusting for age, sex, years of education and APOE ε4 allele indicate that higher adiponectin levels were significantly associated with the increased risk of all-cause dementia, AD and MD, but not with VaD and MCI." (PMID 28421328, 2017). "APOE’s specific association with δ suggests it may have a role in determining all cause dementia risk, not just AD risk." (PMID 28291794, 2017). "Furthermore, as expected, age, APOE e4 status, clinical dementia rating–sum of boxes (CDR-SOB), mini mental status examination (MMSE), logical memory immediate recall, and logical memory delayed recall exhibited significant differences across the five groups (p < 0.001)." (PMID 28558704, 2017). "Thus, observed dementia status must be largely determined by age and APOE independent factors." (PMID 28291794, 2017). "In order to elucidate the clarify in risk of non-communicable diseases, including dementia and AD, between members of the Lao Loum majority and ethnic minorities, we investigated APOE ε4 frequency, anthropometric characteristics, blood pressure, and blood glucose." (PMID 27168072, 2016). "Interestingly, subjects without dementia who have the APOE ε4 allele have been shown to exhibit increased WMH volume." (PMID 25984242, 2015). "Within the limits of our relatively limited knowledge of the genetic factors that influence dementia risk, where statistically tested, addition of novel (non-APOE) risk factors to prediction models do not appear to significantly increase discriminative accuracy." (PMID 26334524, 2015). "We could not assess the combined effects of smoking and APOE ε4 allele on all-cause dementia and VaD because of few individual studies exploring it." (PMID 25763939, 2015). "Differences are mainly in the addition of novel (non-traditional) dementia risk variables, information on diet, depression symptomology, ethnicity, and extension of genetic analysis to include non-APOE genes." (PMID 26334524, 2015). "In the general population without dementia, ApoE e4 is associated with relative cognitive decline at age 79 years, but healthier lipid profiles, such as higher erythrocyte ω-3 polyunsaturated fatty acid content, are significant only in the absence of the ApoE e4 allele." (PMID 24888381, 2014).
dementia (continued). "However, a modified AD-GRS without APOE was associated with slightly larger effects on dementia probability for NHB than NHW." (PMID 25328845, 2014). "Due to the register-based approach, we were unable to adjust for lifestyle-based confounders or genetic risk factors, such as apolipoprotein E ε4-allele, which has been suggested to be a risk factor for hip fracture, independent of the effect of dementia and falling." (PMID 23527106, 2013). "Patients with long-term and severe dementia, however, might show functional connectivity patterns determined by the cognitive level or disease-specific factors rather than by the APOE susceptibility gene." (PMID 23050006, 2012). "The combination of telomere length and APOE-4 did not confer a significantly higher dementia risk." (PMID 22482072, 2012). "The potential influence of APOE variants on anxiety and cognition in AD does not show a clear parallelism, suggesting that other more complex mechanisms are involved in the onset of anxiety in dementia." (PMID 22482072, 2012). "The APOE ε4 variant also influences cognition in healthy adults without dementia." (PMID 23304508, 2012). "Notably, APOE-4 increases the risk of transition to clinical MCI but does not affect the risk for a final transition to dementia, and baseline hypertension decreases the risk of transition to dementia from clinical MCI." (PMID 22536535, 2012). "This may be particularly important given that APOE isoforms themselves may be associated with increased risk of dementia and CAD although we are not aware of studies relating APOE isoforms to early mortality." (PMID 22874105, 2012). "Among susceptibility genes, the apolipoprotein E (APOE) gene (19q13.2) (AD2) is the most prevalent as a risk factor for AD, especially in those subjects harboring the APOE-4 allele, whereas carriers of the APOE-2 allele might be protected against dementia." (PMID 22482072, 2012). "After controlling for compositional differences in APOE genotype (the risk conferring e4 allele being more common in 'mixed' and 'black' ethnic identity groups), there was a non-significant trend towards lower dementia prevalence in those 'non-white' groups." (PMID 21435264, 2011). "In a sensitivity analysis, after merging the 'mixed' and 'black' groups, the interaction between APOE e4 and ethnic identity showed a non-significant trend towards a weaker APOEe4 dementia association among non-whites compared with whites (PR 0.74, 95% CI 0.45-1.24)." (PMID 21435264, 2011). "Finally, the study did not include genetics (e.g., APOE 4) for investigation, which would confound the associations of risk factors with dementia." (PMID 21966372, 2011). "However further larger studies have failed to confirm this impact of apoE genotype on HIV-associated dementia prevalence." (PMID 20109174, 2010). "However, when the APOE-ε4 non-carrier group was further subdivided into neutral and low genetic risk categories, lower APOE genetic risk was found to amplify the impact of low eBMD on incident dementia risk." (PMID 40668308, 2025). "In plots exploring neuropathological diagnoses by APOE genotype and CDR status, we observed an APOE gene dose response for higher frequencies of AD pathology across groups with normal cognition to dementia." (PMID 41268805, 2025). "The percentage of APOE ε4 carriers was higher in the MCI and AD dementia groups compared with the CU‐non AD and SNAP groups." (PMID 40547941, 2025). "For instance, carriers of the ε4 allele of the apolipoprotein E (APOE) gene with a high 10-year coronary heart disease risk (dependent upon vascular risk factors such as higher total cholesterol and lower HDL-cholesterol), may have slower cognitive decline in the mild dementia stage." (PMID 40834163, 2025).
dementia (continued). "On the other hand, the decrease in dementia risk associated with higher serum ergothioneine levels was consistently observed across all subgroups of other risk factors except for obesity, smoking habits, and APOE‐ε4 carriage, without evidence of heterogeneity (all P for heterogeneity >0.10)." (PMID 40908798, 2025). "As dementia diagnosis has the highest weight in the HFRS formula, the most influential peak expectedly resided in the APOE (rs7412) region on chromosome 19." (PMID 40764432, 2025). "SD-pQTLs of the proteins APOE (rs157581, chr19: 45,395,714) and SNAP25 (rs4420638, chr19: 45,422,946) exhibited a sex dimorphic effect on dementia, suggesting potential sex-dimorphic pleiotropy involving these proteins and dementia." (PMID 40877285, 2025). "Dementia diagnoses were determined using available Electronic Health Records (EHR) and APOE genotype was determined using whole-genome sequencing." (PMID 40568661, 2025). "This large multicenter study aimed to estimate the prevalence of tau pathology as measured by PET as a function of Aβ status, age, APOE genotype and sex in CU individuals, individuals with MCI and individuals with dementia." (PMID 40670684, 2025). "Exploratory analyses that examined whether age (dichotomized at the sample median at Visit 2), APOE ɛ4 status, presence versus absence of depressive symptoms, or educational level modified the association between mid‐life social relationships and dementia were not statistically significant." (PMID 40660753, 2025). "In contrast, those experiencing high social adversity had elevated dementia risk regardless of genotype (reference: APOE-ε3/ε3 with social advantage; APOE-ε2 HR = 3.26, 95%CI = 2.06–5.16; APOE-ε3/ε3 HR = 3.12, 95%CI = 2.47–3.95; APOE-ε4 HR = 3.21, 95%CI = 2.34–4.41)." (PMID 41264567, 2025). "Within the combined PREVENT Dementia and ALFA cohorts, APOE ε4 carriers had a steeper decline in white matter integrity from age 60,43 although no volumetric differences were found using voxel‐based morphometry." (PMID 40356022, 2025). "Furthermore, integrating genetic and epigenetic analyses—such as the role of circadian regulation genes (e.g., CLOCK and BMAL1) or APOE variations—could elucidate individual variability in sleep-dementia pathways and support the development of personalized interventions." (PMID 40214959, 2025). "Additionally, the study suggests a potential interaction between the EAT-Lancet diet and APOE ε4 status in relation to AD and all-cause dementia, with a risk-reducing effect observed with several of the scores among APOE ε4 non-carriers, but not among APOE ε4 carriers." (PMID 40222839, 2025). "For APOE ε4 homozygotes, again the AGR was highest for incident dementia at 7.23 (4.55–11.54); for prevalent dementia the AGR was 3.13 (2.63–3.73); for proxy dementia the AGR was 3.51 (2.93–4.21)." (PMID 40568661, 2025). "The ApoE-ε4 positivity rate is expected to be much higher in MCI and dementia patients than in healthy controls." (PMID 40416737, 2025). "For the APOE ε4 heterozygotes, the adjusted generalized ratio (AGR) (95% CI) was highest for incident dementia at 2.95 (2.31–3.74)." (PMID 40568661, 2025). "Relative to A-T-, all other groups displayed higher rates of APOE ε4 carriership, higher CDR-SoB score and greater prevalence of MCI or dementia diagnosis." (PMID 40016526, 2025). "To account for the fact that some control participants may be mislabeled because of a short history of EHR visits, we restricted our dataset to only individuals with greater than one year of EHR visits (n = 218,542) and found that this did not affect the association between APOE and dementia status." (PMID 40568661, 2025). "The APOE genotype was available for 24 participants: 16 in the MCI group and 8 in the dementia group." (PMID 41008272, 2025). "Complete data on PSQI scores, depression, APOE genotype, and hypothalamic volume was available for 857 participants (PREVENT Dementia: 559, ALFA+ [sub‐study]: 298)." (PMID 40356022, 2025).
dementia (continued). "Both APOE-ε4 genotype (OR = 1.2, p = 0.01) and RVI-AD (OR = 1.7, p = 5·10−5) contributed to dementia conversion over the 12-year follow-up period." (PMID 41001540, 2025). "Predictors included APOE ε4 carrier status, Centiloid (CL) value, clinical disease stage (SCD, MCI, dementia), and the time interval between PET and lumbar puncture." (PMID 41238774, 2025). "Furthermore, the association between higher adherence to the EAT-Lancet diet and reduced risk of all-cause dementia among APOE ε4 non-carriers remained with the Knuppel score, the Hanley-Cook score, and the Bui score, and with the Kesse-Guyot score in relation to AD." (PMID 40222839, 2025). "We note that in both APOE ε4 heterozygotes and homozygotes, the prevalent and proxy dementia AGR was significantly lower than the incident dementia AGR (95% confidence interval limits)." (PMID 40568661, 2025). "Moreover, individuals with low-to-moderate APOE risk exhibited stronger protective associations of PUFA, N6FA, DHA, and LA intake against the onset of dementia, and from N3FA and DHA intake against dementia-related mortality, compared to those with higher APOE risk (ε3/ε4 and ε4/ε4)." (PMID 40695676, 2025). "Thus it is likely that APOE causes more rapid progression in PD as marked by both dementia and mortality, but we did not have the cause of death or cognition data in the majority of our cohorts to determine the extent to which PD dementia contributes to mortality." (PMID 38849413, 2024). "For the APOE ε4 gene, the reverse was true, with this gene being in higher proportions in the MCI and dementia group." (PMID 39044522, 2024). "Interestingly, Apolipoprotein (APOE) ε4 carriership, which is most commonly associated with late onset AD, was also included in the SCD-plus criteria, enhancing the hypothesis of an association between SCD and genetic predisposition for dementia." (PMID 38534745, 2024). "However, whether and how APOE ε4 affects brain health in non-dementia aging is unknown." (PMID 38605018, 2024). "LX1001 is being evaluated in an open‐label, dose‐escalation Phase 1/2 clinical trial in APOE ε4 homozygous individuals who are 50 years of age or older and have mild cognitive impairment (MCI) to moderate dementia and biomarkers consistent with AD." (PMID 39031528, 2024). "Additionally, we could not account for genetic susceptibility genes, such as apolipoprotein E, with an established role in the development of dementia." (PMID 39684995, 2024). "In mild dementia, retained time-constant effects were sex and CSF pTau and retained time-varying effects were age, baseline MMSE, APOE ε4, and CSF Aβ1–42." (PMID 38986053, 2024). "A meta-analysis in non-dementia cohorts has shown that amyloid positivity, determined through amyloid PET imaging and CSF biomarkers, is exacerbated during aging in an APOE genotype-dependent manner (ε4/ε4 > ε3/ε4 = ε2/ε4 > ε3/ε3 > ε2/ε3 > ε2/ε2)." (PMID 38336940, 2024). "However, it is unclear whether APOE e4 drives dementia via AD pathology or independently." (PMID 37987016, 2023). "In conclusion, in a pooled analysis of DLB, PD and PDD we have shown that APOE and variation at the 5’ end of the SNCA gene are the major determinants of LBD with dementia." (PMID 37987016, 2023). "These epistatic effects may contribute substantially to the variation in disease susceptibility; that is, people carrying risk factors for LOAD but resilient to the disease, as well as people carrying the risk allele APOE*4 who live into their 90s without developing dementia." (PMID 37621137, 2023). "Further, even among the APOE Ɛ4 non-carriers, the “L” allele frequency was significantly higher in cases than in controls (p < 0.0008) showing that the L allele on its own may also be a risk factor for dementia in our sample set." (PMID 38028602, 2023). "There were, as expected, significant differences in age, APOE status, MMSE score, Aβ status, and Aβ-PET and tau-PET SUVR between the CU, MCI, and dementia groups (p < 0.001)." (PMID 37137722, 2023).